ASH1L (ASH1 like histone lysine methyltransferase)
Description:
Histone methyltransferase specifically trimethylating 'Lys-36' of histone H3 forming H3K36me3. Also monomethylates 'Lys-9' of histone H3 (H3K9me1) in vitro (By similarity). The physiological significance of the H3K9me1 activity is unclear (By similarity).
Synonyms: huASH1; KMT2H; ASH1; ASH1L1; MRD52
Tractability: Small molecule: a structure with a bound ligand is known; a high-quality ligand is known; it has a high-quality binding pocket. PROTAC: UniProt records ubiquitination sites on it; ubiquitination databases record sites on it; a small molecule that binds it is known.
Target class: Writer; Protein methyltransferase; SET domain; Epigenetic regulator
Chemical probes: AS-99 (high quality)
Gene: Protein-coding gene on chromosome 1 (155,335,268 to 155,563,162, reverse strand). Ensembl gene ENSG00000116539.
Subcellular location: Nucleus; Cell junction, tight junction; Chromosome
Subcellular location (Human Protein Atlas): Golgi apparatus; Nucleoplasm; Nuclear bodies
Pathways (Reactome):
Chromatin organization: PKMTs methylate histone lysines
Gene Ontology:
Molecular function: histone H3K36 methyltransferase activity; histone H3K36 trimethyltransferase activity; histone H3 methyltransferase activity; histone H3K4 methyltransferase activity; histone H3K9 methyltransferase activity; histone H3K9 monomethyltransferase activity; chromatin binding; DNA binding; histone methyltransferase activity
Biological process: regulation of DNA-templated transcription; chromatin remodeling
Cellular component: nuclear body; nucleoplasm; nucleus; bicellular tight junction; chromosome; nuclear lumen
Genetic constraint (gnomAD): Loss-of-function variants: 18 observed, 255.76 expected, observed/expected ratio (o/e) 0.0704, 90% interval 0.048 to 0.1. The upper end of that interval is the gene's LOEUF score, 0.1, which puts it in group 1 of 6, group 1 being the genes least tolerant of losing a copy. Missense variants: 2,836 observed, 3,628.2 expected, observed/expected ratio (o/e) 0.78, 90% interval 0.76 to 0.81. Synonymous variants: 1,148 observed, 1,287.7 expected, observed/expected ratio (o/e) 0.89, 90% interval 0.85 to 0.94.
Gene-disease validity (ClinGen):
ClinGen rates the evidence that ASH1L causes each of these diseases.
syndromic complex neurodevelopmental disorder (autosomal dominant): Definitive. A disorder that involves more than one phenotype associated with the central nervous system, including but not limited to intellectual disability, autism, and seizures (epilepsy), and also a distinctive pattern of other features including dysmorphisms and/or congenital malformations.
Homologues: Orthologues: chimpanzee ASH1L (99% identical), macaque ASH1L (99% identical), rabbit ASH1L (96% identical), pig ASH1L (95% identical), dog ASH1L (94% identical), guinea pig ASH1L (94% identical), rat Ash1l (93% identical), mouse Ash1l (92% identical), tropical clawed frog ash1l (58% identical), zebrafish ash1l (48% identical), Drosophila melanogaster ash1 (13% identical), Caenorhabditis elegans met-1 (8% identical), and 12 more. Paralogues in human: SETBP1 (15% identical), NSD1 (9% identical), SETD2 (9% identical), KMT2D (8% identical), NSD2 (7% identical), NSD3 (7% identical), KMT2C (7% identical), KMT2A (7% identical), KMT2B (6% identical), SETD1B (6% identical), EHMT1 (6% identical), SETD1A (6% identical), and 7 more.
Diseases named in the same sentence as ASH1L in open-access papers:
ASH1L is named in the same sentence as 77 diseases in open-access papers, as found by Europe PMC text mining. Sharing a sentence is not in itself a finding about the gene and the disease. The quoted sentences say what the papers report.
Intellectual disability (14 papers, 2020 to 2025). "Mutations in ASH1L have been associated with a range of phenotypes, including intellectual disability (ID), autism spectrum disorder (ASD), attention deficit hyperactivity disorder (ADHD), seizures, as well as differences in skeletal, muscular, and sleep functions." (PMID 39902220, 2025). "Pathogenic ASH1L variants have been reported in probands with broad phenotypic presentations, including intellectual disability, autism spectrum disorder, attention deficit hyperactivity disorder, seizures, congenital anomalies, and other skeletal, muscular, and sleep differences." (PMID 38674358, 2024). "The range of neurodevelopmental features observed in individuals with pathogenic variants in ASH1L is broad and includes intellectual disability (ID) and autism spectrum disorder (ASD), with variable presence of congenital anomalies and non-specific dysmorphic features." (PMID 38674358, 2024). "The clinical manifestations caused by ASH1L mutations are extensive phenotypic heterogeneity, such as intellectual disability, autosomal dominant 52 (MRD) and Tourette syndrome, suggesting the common genetic risk of ASH1L for clinically distinct syndromes." (PMID 39766886, 2024). "ASH1L is one of the highest risk genes associated with autism spectrum disorder (ASD) and intellectual disability (ID)." (PMID 35449559, 2022). "Recent genetic and clinical studies report that mutations of the epigenetic gene ASH1L are highly associated with human ASD and intellectual disability (ID)." (PMID 34145365, 2021). "Knockdown of Ash1L in PFC of juvenile mice induces the downregulation of risk genes associated with ASD, intellectual disability (ID) and epilepsy." (PMID 34782621, 2021). "Interestingly, genes connecting pairs of 16p11.2 genes were enriched for genes intolerant to functional variation, such as ASH1L, a histone methyltransferase activator and autism candidate gene, and CAMK2B, a protein kinase gene causative for intellectual disability." (PMID 33819264, 2021). "Research highlights the role of Ash1l, a gene highly expressed in the brain, which correlates with the neuropathology of TS, ASD, and intellectual disability." (PMID 40094948, 2025).
leukemia (14 papers, 2017 to 2025). A malignant (clonal) hematologic disorder, involving hematopoietic stem cells and characterized by the presence of primitive or atypical myeloid or lymphoid cells in the bone marrow and the blood. "The histone methyltransferase ASH1L has been linked to tumorigenesis, mainly in leukemia." (PMID 40394007, 2025). "It is worth noting that ASH1L also co-localized with HIF-1α on the promoter regions of genes in leukemia cells; however, only 32.5% (1132 in 3482) of ASH1L target genes were shared with HIF-1α, which are distinct from those in metastatic PCa." (PMID 40394007, 2025). "Given ASH1L’s crucial role in leukemogenesis, small-molecule inhibitors have been developed and tested in preclinical leukemia models." (PMID 40394007, 2025). "It is worth noting that, in leukemia, ASH1L plays a key role in activating HOX family genes that facilitate leukemogenesis." (PMID 40394007, 2025). "The synergistic action of two methylases: KMT2A/MLL1 (methylates H3K4, see next section) and ASH1L (KMT2H), is associated with leukemogenesis and with regulation of HOX gene expression in leukaemias with KMT2A translocations." (PMID 35406676, 2022). "Based on our findings demonstrating the importance of the ASH1L SET domain in MLL leukemia, we evaluated the effect of the ASH1L inhibitors in a panel of leukemia cells with MLL1 translocations." (PMID 33990599, 2021). "Here the authors present small molecule inhibitors of ASH1L and demonstrate their on-target activity in leukemia cells and a mouse model of leukemia." (PMID 33990599, 2021). "A recent study demonstrated that ASH1L is a crucial regulator of key leukemia target genes and contributes to leukemia pathogenesis." (PMID 28055972, 2017). "Indeed, treatment with AS-99 resulted in a reduced number of H3K36me2 peaks when compared to the DMSO-treated cells, confirming that AS-99 blocks the enzymatic activity of ASH1L in the MLL1-rearranged leukemia cells." (PMID 33990599, 2021). "Additionally, miR-142 targets ASH1L/KMT2H in leukemia and thyroid cancer, miR-675 regulates SUV39H2/KMT1B in liver cancer, miR-122 influences SUV39H1/KMT1A in hepatocellular carcinoma, and miR-101 modulates KMT6/EZH2 in non-small cell lung cancer (NSCLC), prostate, and renal cancers." (PMID 40761244, 2025). "However, NUP98:NSD1 fusions occur frequently in pediatric AML and are associated with poor prognosis, an NUP98:ASH1L fusion was recently identified by optical gene mapping in secondary AML, and ASH1L also appears to play a role in leukemia driven by MLL1:AF9 fusion." (PMID 39403928, 2024). "Therefore, ASH1L has been proposed as a possible therapeutic target in leukaemia." (PMID 35406676, 2022). "Finally, we performed gene expression studies in MLL-AF9 and MLL-AF6 transformed bone marrow cells and found that genes highly relevant to MLL leukemia (Hoxa5, Hoxa9, Hoxa10, Meis1, and Mef2C) were expressed at much lower levels in the ΔSET Ash1l versus WT Ash1l cells." (PMID 33990599, 2021). "Thus, both of these two bromodomain-containing methyltransferases appear to contribute to leukemia development, and ASH1L may provide a new avenue for targeted treatment strategies." (PMID 34298819, 2021). "The histone lysine demethylase KDM2A was described to be an opposing regulator of ASH1L by specifically demethylating H3K36me2, which leads to the dissociation of KMT2A/PS1P1 and the decreased description of KMT2A target leukemia genes." (PMID 37296904, 2023). "The inhibition of ASH1L’s SET-domain led to downregulation of the HOX gene expression and induced apoptosis and differentiation in KMT2A::MLLT3-transformed leukemia cells." (PMID 37296904, 2023). "To determine the role of ASH1L in the MLL-AF9-induced leukemogenesis in vivo, we performed leukemia transplantation assays and monitor the leukemia development in recipient mice." (PMID 34692539, 2021).
leukemia (continued). "When applied in vivo, AS-99 reduced the leukemia burden in a systemic model of MLL leukemia, supporting the inhibition of ASH1L as an approach to target leukemia with MLL1 translocations." (PMID 33990599, 2021). "At the molecular level, ASH1L maintains the H3K36me2 mark, which enables the recruitment of the MLL1 protein complex to chromatin to activate target gene expression in leukemia cells." (PMID 33990599, 2021). "To evaluate the potential therapeutic effects of the ASH1L inhibitors, we performed an in vivo study with AS-99 using a xenotransplantation model of MLL leukemia with MV4;11 cells expressing luciferase transplanted into NSG mice." (PMID 33990599, 2021). "To evaluate the mechanism of action of the ASH1L inhibitors, we performed gene expression studies with AS-99 and AS-nc in MOLM13 and MV4;11 MLL leukemia cells harboring MLL-AF9 and MLL-AF4 translocations, respectively." (PMID 33990599, 2021). "Although the co-localization of ASH1L and HIF-1α found in both metastatic tumors and leukemia suggests a universal mechanism of gene regulation, their co-target genes in metastatic cells are distinct from those in leukemia." (PMID 40394007, 2025). "miR-142 could inhibit ASH1L (KMT2H), and its downregulation leads to increased levels of ASH1L in leukemia." (PMID 35087589, 2022). "However, the first-in-class inhibitor of the ASH1L SET domain, AS-99, has shown remarkable anti-leukemic activity against MLL1 fusion leukemia, suggesting that ASH1L can be potentially targeted for the therapeutic cancer treatment." (PMID 36033518, 2022). "Furthermore, genetic deletion of ASH1L in the MLL-AF9-transformed cells impaired the maintenance of leukemic cells in vitro and largely blocked the leukemia progression in vivo." (PMID 34692539, 2021). "Thus, our study revealed the critical functions of ASH1L in promoting the MLL-AF9-induced leukemogenesis, which provides a molecular basis for targeting ASH1L and its enzymatic activity to treat MLL-AF9-induced leukemias." (PMID 34692539, 2021). "Moreover, there appears to be some functional overlap between ASH1L and MLL in leukemia pathogenesis." (PMID 34298819, 2021). "This action supports a role of ASH1L in MLL-mediated leukemia oncogenesis and indicates that it could be a target for leukemia therapy." (PMID 30466474, 2018). "Ash1l, Ctnnb1, Hoxa7, and Hoxa9 were also upregulated in the single mutant Mir-142−/− GMPs compared to WT, but the key co-factors Meis1 and Pbx3 were not, potentially explaining why these mice failed to develop leukemia." (PMID 33173219, 2020). "In addition, ASH1L can promote the recruitment of lens epithelium-derived growth factor (LEDGF) and other proteins in the chromatin of key target genes of leukemia and is a key regulator of mixed-lineage leukemia (MLL)-dependent transcription and leukemia transformation." (PMID 36094439, 2022). "Thus, our study revealed the critical functions of ASH1L in MLL-AF9-induced leukemogenesis and raised the possibility that ASH1L might serve as a potential therapeutic target for the treatment of MLL-AF9-induced leukemias." (PMID 34692539, 2021). "However, the roles of ASH1L and its enzymatic activity in the development of MLL-rearranged leukemias are not fully elucidated in Ash1L gene knockout animal models." (PMID 34692539, 2021). "Similarly, pharmacologic inhibition of ASH1L with AS-99, but not AS-nc, induced differentiation in MLL leukemia cells (MV4;11 and KOPN8) as assessed by markedly (up to 50%) increased expression of the CD11B differentiation marker and cell morphology changes." (PMID 33990599, 2021).
autism (12 papers, 2018 to 2024). Persistent deficits in social interaction and communication and interaction as well as a markedly restricted repertoire of activity and interest as well as repetitive patterns of behavior. "This study identified synaptic mechanisms underlie the autism-like social deficits and epilepsy in Ash1l+/GT mice, which provides potential therapeutic development for patients carrying ASH1L mutations." (PMID 39766886, 2024). "Chemogenetic inhibition of PFC is sufficient to ameliorate autism-like social deficits and abolish absence-like seizures in Ash1l+/GT mice, which reveal potential therapeutic strategies for the treatment of ASH1L-associated ASD and epilepsy." (PMID 39766886, 2024). "Elevated excitability of pyramidal neurons in the PFC is strongly implicated in autism-like behavioral deficits and absence-like seizures in Ash1l+/GT mice." (PMID 39766886, 2024). "To determine the synaptic mechanisms underlying the autism-like social deficits and absence-like seizures in Ash1l+/GT mice, we performed whole-cell patch-clamp recordings in PFC slices." (PMID 39766886, 2024). "The pathophysiological mechanisms underlying these autism-like behaviors caused by Ash1L deficiency and therapeutic strategies to rescue these abnormalities will be investigated in future studies." (PMID 34782621, 2021). "De novo mutations in ASH1L have been identified in multiple people with autism, while rarely occurring in controls." (PMID 32912160, 2020). "In this study, we used a germline Ash1l knockout mouse model and found that Ash1l haploinsufficiency causes autism-like behavioral deficits, absence-like seizures, and increases the susceptibility for PTZ-induced convulsive seizures, confirming the causal role of ASH1L in ASD and epilepsy." (PMID 39766886, 2024). "However, the underlying synaptic mechanisms of how ASH1L haploinsufficiency contributes to autism-related social deficits and seizures are largely unknown." (PMID 39766886, 2024). "ASH1L haploinsufficiency is strongly linked to autism, despite the unknown mechanism." (PMID 34782621, 2021). "Considering the variable syndromic phenotypic features reported, the ClinGen Intellectual Disability and Autism Gene Curation Expert Panel curated ASH1L in relationship to syndromic complex neurodevelopmental disorder." (PMID 38674358, 2024). "Using the DREADD-based strategy, we found that chemogenetic inhibition of pyramidal neurons in the PFC ameliorated autism-like social deficits and abolished absence-like seizures in Ash1l+/GT mice." (PMID 39766886, 2024). "In this study, we characterized the impact of Ash1l haploinsufficiency on autism-related behaviors and seizures in a mouse model generated by a gene-trap (GT) knockout strategy." (PMID 39766886, 2024). "Ash1l haploinsufficiency or conditional knockout Ash1l in neural progenitor cells induced autism-like behavioral deficits." (PMID 39766886, 2024). "We demonstrated the potential for polymorphisms affecting transcription by analyzing the CNS for ASH1L, an autism candidate gene." (PMID 32912160, 2020). "Ash1L is involved in several pathological conditions, including autoimmune disease, autism, and cancer." (PMID 30487570, 2018). "After whole exome sequencing of 100 trios (TS patients and their parents), point mutations in ASH1 Like Histone Lysine Methyltransferase (ASH1L) causing defects in its enzymatic activity were identified as a susceptibility gene for TS9, previously associated with mental retardation and autism." (PMID 33500781, 2020). "In contrast, for 134 autism-associated genes, including ASH1L, ANK2 and SHANK3, we could identify at least one carrier of an S-LoF among the undiagnosed individuals, suggesting lower effect sizes on autism diagnosis." (PMID 37365347, 2023).
autism (continued). "However, when we extended observation time to 10 min, the Ash1L-Nes-cKO mice show increased locomotor activity compared to wild type (t = 2.496, df = 36, p = 0.017), suggesting that they may be hyperactive, a phenotype also sometimes found in autism patients." (PMID 34145365, 2021). "Ash1L is an epigenetic activator belonging to the Trithorax group of proteins and is involved in FSHD muscular dystrophy, autism and cancer." (PMID 30487570, 2018). "ASH1L (absent, small, or homeotic-like 1), a histone methyltransferase, is a high-risk gene for ASD based on identified high phenotypic penetration disease-causing loss-of-function (LOF) mutations (Simons Foundation Autism Research Initiative, SFARI)." (PMID 39766886, 2024).
autism spectrum disorder (8 papers, 2021 to 2025). A spectrum of developmental disorders that includes autism, and Asperger syndrome. "ASH1L, a histone methyltransferase, is identified as a top-ranking risk factor for autism spectrum disorder (ASD), however, little is known about the biological mechanisms underlying the link of ASH1L haploinsufficiency to ASD." (PMID 34782621, 2021). "KCNQ2 and ASH1L are linked to epilepsy and autism spectrum disorder." (PMID 38283851, 2024).